AR (androgen receptor)
Diseases named in the same sentence as AR in open-access papers (continued):
Sharing a sentence is not in itself a finding about the gene and the disease.
breast carcinoma (continued). "Currently, there have been few studies on AR in neoadjuvant therapy for breast cancer, and some studies have suggested that AR positivity may be associated with poor neoadjuvant outcomes in TNBC." (PMID 36556209, 2022). "Androgen receptor (AR) expression is frequently observed in breast cancer, but its association with estrogen receptor (ER) expression in breast cancer remains unclear." (PMID 36232774, 2022). "Importantly in the context of AR-positive breast cancers and QNBC, recent efforts have identified androgen-responsive miRNAs, the expression of specific miRNAs and miRNA expression profiles that are associated with AR expression in breast cancer." (PMID 35203574, 2022). "Previous studies have suggested that an increased androgen receptor positivity is a risk factor in the development of breast cancers in female-male transexuals and few cases of breast cancer were reported in transgender males receiving testosterone therapy for gender-affirming hormonal treatment." (PMID 35784659, 2022). "In hormone receptor (HR)-positive breast cancers, AR expression is associated with better outcomes." (PMID 35207749, 2022). "Androgen receptor (AR) is strong association with breast cancer (BRCA)." (PMID 36450882, 2022). "Several other studies have also revealed that the expression of AR in ER + ve breast cancer is associated with a smaller size, lower histopathological grading, and lower proliferative properties of the tumors, which might prolong the patients’ survival." (PMID 35053220, 2022). "Only a few studies have evaluated miRNA in association with AR status in breast cancers." (PMID 36550153, 2022). "AR is a member of the steroid hormone receptor family, and there are emerging pieces of evidence on the associations between androgen effect and tumorigenesis in breast cancer." (PMID 36178912, 2022). "Putative AR Deregulated miRNAs and associated cancer hallmarks in breast cancers." (PMID 36111296, 2022). "Finally, using a mutational strategy, we provide evidence showing that Kindlin-2-mediated associations with AR and Src are crucial for AR Tyr-534 phosphorylation, its downstream signaling, breast cancer cell proliferation and migration." (PMID 35595729, 2022). "Even though AR is expressed at a lower rate in TNBC than in other breast cancers, its presence could still be useful in diagnostic and prognostic evaluation and could provide novel insights important for managing such challenging tumor." (PMID 33915941, 2021). "The androgen receptor (AR) is frequently expressed in breast cancer (BC), but its association with clinical and biological parameters of BC patients remains unclear." (PMID 34571711, 2021). "Importantly, AR is commonly expressed in breast cancers and is associated with poor prognosis of patients." (PMID 34659545, 2021). "Notably, FOXA1 also facilitates AR-chromatin association in prostate development and cancer as well as in breast cancer cells." (PMID 34680352, 2021). "This review aims to elucidate whether AR activity might impact on breast cancer susceptibility by collecting evidences of AR-dependent signalling in normal breast epithelium and on its relationship with well-known breast cancer risk factors." (PMID 35008851, 2021). "ZNF467 has not been functionally characterized, however, a recent study suggests that it is a transcription factor which clusters in close proximity to the androgen receptor in a network associated with breast cancer risk, indicating that ZNF467 and AR regulate similar pathways." (PMID 33585078, 2021).
breast carcinoma (continued). "Therefore, our present study aimed to determine the prevalence of AR expression and its association with clinicopathological parameters in Ethiopian breast cancer patients." (PMID 32374753, 2020). "The majority of studies suggest that AR expression in ER+ breast cancer is associated with a favorable prognosis; however, other studies do not support a prognostic and predictive value of AR expression in ER+ breast cancer." (PMID 32210163, 2020). "The high AR expression group was significantly associated with superior overall survival and disease-free survival when compared with the low AR expression group with breast cancer patients." (PMID 32290220, 2020). "There is a significant association between AR and ER expression in breast carcinoma." (PMID 32075053, 2020). "Thus, our study demonstrated that the molecular subtypes of breast cancer differ in the expression profiles of AR and its associated miR-205, miR-185, and miR-21." (PMID 32373367, 2020). "The protein level of AR is significantly associated with disease outcome in breast cancer." (PMID 31126320, 2019). "Population-based studies support the hypothesis that AR may antagonize the detrimental effects of ER signaling, and have shown a consistent inverse association between tumor AR expression and mortality among patients with ER+ breast cancer." (PMID 30795773, 2019). "Moreover, we consider findings about involvement of AR signaling in all stages of BC, highlighting its association with different subsets of breast carcinomas and with pre- and postmenopausal state of patients." (PMID 30941159, 2019). "Serum PSA levels were weakly associated with serum testosterone levels and AR positivity in primary tumors suggesting that sPSA may reflect some tumor biological properties including androgen signals in post-menopausal breast cancer." (PMID 31664946, 2019). "In breast cancer this mainly occurs via mutations resulting in overexpression of hormone receptors including the estrogen receptor (ER), androgen receptor (AR), epidermal growth factor receptor (EGFR), human epidermal growth factor receptor 2 (HER2) and their corresponding ligands." (PMID 31666932, 2019). "Interestingly, in 434 patients with recurrent breast cancer, higher levels of the AR target gene, PSA, have been associated with poor response to tamoxifen therapy and decreased overall survival." (PMID 30416486, 2018). "We assessed AR expression in a total of 1258 patient at both the mRNA and protein levels, and found that loss of AR is associated with earlier breast cancer diagnosis (3 years earlier in all patients and 7 years earlier in AA patients), a shorter time to progression, and a worst overall survival." (PMID 29912871, 2018). "Furthermore, Cochrane and coworkers demonstrated that AR:ER ≥ 2 was associated with an increased risk of tamoxifen failure in breast cancer." (PMID 30547831, 2018). "Many of these genes have been implicated in breast cancer and coupled with the dichotomous levels of androgenic steroid present, this warrants further investigation particularly in the context of active tumor promoting AR signaling." (PMID 30416486, 2018). "Thus, loss of AR in breast cancer patients appears to be a prognostic biomarker, with increased capacity for AA women." (PMID 29912871, 2018). "AR expression is associated with a well-differentiated state and with more indolent breast cancers." (PMID 30547831, 2018). "Furthermore, higher dihydrotestosterone (DHT) levels are associated with a favorable prognosis in AR-positive breast cancer cells." (PMID 29713287, 2018). "Finally, we explored the relationships between established breast cancer risk factors and AR expression in normal tissue." (PMID 30276234, 2018). "This study will also provide evidence to determine whether AR-targeted immunohistochemistry of breast cancer samples is a useful diagnostic tool for early detection of metastasis breast cancer." (PMID 29254284, 2017).
breast carcinoma (continued). "In addition, we conducted an exploratory analysis of early pregnancy hormones and breast cancer risk by tumor androgen receptor (AR) status; to our knowledge, this is the first investigation of early pregnancy hormones and breast cancer risk by AR status." (PMID 28720108, 2017). "Besides data from a systematic review and meta-analysis included nineteen studies with a total of 7693 women showed that expression of AR in women with breast cancer was associated with better overall survival (OS) and DFS irrespective of ERα status." (PMID 28474005, 2017). "In prostate and breast cancers, AR expression has been associated with a favorable prognosis." (PMID 28938615, 2017). "Similarly, previous studies showed that post-menopausal breast cancer patients have high testosterone levels and high expression of AR, which were significantly associated with the ER+ status of the tumors (OR 2.42; 95% CI, 1.22-4.82)." (PMID 29254284, 2017). "When these networks were merged, AR was the key node for the two cancer-related networks, suggesting that aberrant activation of these signaling pathways may play a key role in adult mammary tumor risk." (PMID 28487351, 2017). "Further, DHT was detected at higher concentrations in breast cancer tissues, supporting the hypothesis that a combination of AR expression and higher DHT levels are associated with a favorable prognosis in AR-expressing breast cancer tissues." (PMID 27918430, 2016). "Nuclear AR expression, which is an indirect measure of activated AR, was associated with favorable prognosis such as smaller tumor size, lower grade, and overall survival, suggesting that AR activation is favorable in breast cancer." (PMID 27918430, 2016). "Despite lacking the DBD, type 3a and 3b AR demonstrated androgen-independent activation of androgen-responsive reporters, and also altered the expression of known AR-target genes in prostate and breast cancer cells, suggesting that the variant AR proteins interact with DNA." (PMID 28035996, 2016). "Additionally, AR/Ar-deficient cell lines were used, e.g. AR-deficient MCF-7 breast cancer cells, to examine the effect on estrogen administration in a system lacking AR." (PMID 26715186, 2015). "Furthermore, more attention was paid to the association between AR expression and clinicopathological characteristics or prognostic value in ER-negative and TN breast cancers." (PMID 25695063, 2015). "An RNA-seq breast cancer dataset from The Cancer Genome Atlas, comprised of 1057 cancers and 111 peri-tumoral samples of normal histology, was used to examine transcripts associated with the AR gene." (PMID 26554309, 2015). "In addition to ER/PR, androgen receptor (AR) is another steroidal hormone that influences and is associated with breast cancers, but the relationship is still not clearly understood." (PMID 25140630, 2014). "Interestingly, androgens and the androgen receptor affect breast cancer risk and prognosis, although the data are somewhat complicated." (PMID 25029565, 2014). "It was also shown that it is possible with microarray data to divide mammary tumors into 3 major groups based on steroid hormone status: luminal (ER+/AR+), basal (ER−/AR−), and molecular apocrine (ER−/AR+) with a certain association between apocrine histology and molecular apocrine type." (PMID 25389781, 2014). "The results revealed that AR expression could predict lower risk of relapse in patients with breast cancer." (PMID 24324816, 2013). "Moreover, androgen receptor (AR) expression is strongly associated with ERα positivity and AR inhibits expression of oestrogen-responsive genes in ERα-positive breast cancer cells." (PMID 24049078, 2013). "Microsatellites in the estrogen receptor (ESR1, ESR2) and androgen receptor (AR) genes have been hypothesized to be predisposing factors for breast cancer but the mechanisms are unknown." (PMID 22792352, 2012).
breast carcinoma (continued). "However, recent studies suggest that overexpression of AR in breast cancer does occur, and is associated with overexpression of ERα and in breast cancers with PIK3CA mutations in the kinase domain." (PMID 22321971, 2012). "The CAG repeat length within the AR gene might be one useful molecular biomarker to identify males at increased risk of breast cancer development." (PMID 23272232, 2012). "AR has been implicated in breast tumourigenesis, however delineating its precise function has proven difficult with AR-mediated androgenic effects shown to both stimulate and inhibit growth of breast cancer cells." (PMID 22471922, 2012). "To conclude, the findings presented in this study indicate that the CAG repeat length within the AR gene might be one useful molecular biomarker to identify males at increased risk of breast cancer development." (PMID 23272232, 2012). "Shorter repeat lengths may also provide an advantage via reduced cancer risk; in a study of women with the BRCA1 allele, shorter CAG repeat lengths within the AR gene were associated with reduced risk of breast cancer." (PMID 22151998, 2011). "Sparse epidemiologic data suggest that a long AR-CAG repeat yielding a less active AR may be associated with increased risk of breast cancer." (PMID 20831839, 2010). "Moreover the present study, to our knowledge, is the first report on association of AR with breast cancer from India." (PMID 20831839, 2010). "Although the role of AR as a potential new target for hormone therapy is recommended and it may serve as clinically useful predictor to therapy, the impact of AR in breast cancer needs further study, especially its association with growth factors." (PMID 20831839, 2010). "Interaction of AR protein is known to be dependent on tissue and promoter context and a decreased amount of AR protein (long CAGn) with low transcriptional activity in the cell would increase the breast cancer risk." (PMID 20831839, 2010). "But even with these limitations, the present study makes a substantial endeavor in enriching our knowledge towards better understanding of androgen receptor gene polymorphism (CAGn) and breast cancer risk as well as its role as a predictive marker in the understudied population of north India." (PMID 20831839, 2010). "Androgens have been hypothesised to influence risk of breast cancer through several possible mechanisms, including their conversion to estradiol or their binding to the oestrogen receptor and/or androgen receptor (AR) in the breast." (PMID 16987421, 2006). "Involvement of the AR in breast tumourigenesis is suggested by the existence of inactivating germline mutations in the hormone-binding domain in male breast cancer patients, and by splice variants that disrupt the transactivation domain in female breast tumours and tumour cell lines." (PMID 15743497, 2005). "This variability in AR expression may be influenced by factors such as tumor microenvironment, hormonal regulation, and genetic mutations, highlighting the complexity of ARs’ role in breast cancer." (PMID 40286049, 2025). "Estrogen receptors (ER) and androgen receptors (AR) function as key drivers in many breast and prostate cancers, respectively, and their ligand-dependent activity underlies the success of endocrine therapies (e.g., anti-estrogens in ER+ breast cancer and anti-androgens in prostate cancer)." (PMID 40650173, 2025). "In our previous study, we demonstrated AR expression in TAMs within breast carcinoma tissues, and a phenotype characterized by 5αRed1-positive and higher macrophage infiltration was strongly associated with more aggressive tumor behavior and poorer clinical outcomes in breast cancer patients." (PMID 39682229, 2024). "Using AI-based technologies to classify AR-associated breast cancer subtypes based on the AR expression level (or expression pattern) plus the expression of ER, PR, or HER2 will help with the selection of treatments that may effectively benefit cancer patients." (PMID 38339092, 2024).
breast carcinoma (continued). "Hence, AR-GATA3 mediated up-regulation of EHF in breast cancer cells may play a key role in mediating the tumor suppressor activity associated with AR signaling." (PMID 38317241, 2024). "To explore Kindlin-2 deficiency-induced inhibition of AR signaling and breast cancer progression is due to the reduction of AR Tyr-534 phosphorylation, we used a phosphor-mimic mutant AR-Y534D (tyrosine 534 replaced by an aspartic acid) to study the function of AR Tyr-534 phosphorylation." (PMID 35595729, 2022). "The most studied is the relation of pesticides with the risk of breast cancer, whose initiation and progression are known to be associated with changes in the expression and activity of estrogen receptor (ER), progesterone receptor (PR), and androgen receptor (AR)." (PMID 35051067, 2022). "There are few reports on ANK3 in cancer, and one showed that ANK3 can be used as a prognostic factor for two primary histologic subtypes of cutaneous melanoma and may be associated with breast cancer prognosis by regulating the androgen receptor signaling pathway." (PMID 35988113, 2022). "Similarly to the trend observed with AR expression, retrospective meta-analyses of patients with ER+ breast cancer have determined that high GR mRNA levels are associated with low tumour grade and better prognosis compared to low or negligible GR expression, independent of PR expression." (PMID 34638457, 2021). "Notably, AR overexpression is associated with breast cancer aggressiveness." (PMID 34659545, 2021). "It has been reported that breast cancer risk may be influenced by indirect effect of androgens via their conversion to estradiol, or by binding with AR to promote or by stopping breast cell growth, or even by binding to ESR1 and inducing proliferation in breast cells." (PMID 30975222, 2019). "This association may mask differential effects of AR signaling in ER+ and ER− breast cancers." (PMID 30795773, 2019). "In this analysis, we evaluated AR expression in normal breast tissue as a potential predictor of subsequent breast cancer risk in a nested case–control study within the Nurses’ Health Study and Nurses’ Health Study II cohorts and whether this association differed by ER co-expression." (PMID 30276234, 2018). "The associations between testosterone and ER+/PR+/AR+ and ER+/PR+ breast cancer risk, among the subset of women with AR data, were similar (among women with AR data: ER+/PR+ ORlog2: 1.32; ER+/PR+/AR+ ORlog2: 1.36), suggesting the AR may not play an important role in this context." (PMID 28720108, 2017). "For example, as epidemiological and case-control studies indicate an association between elevated concentrations of androgens and increased risk of developing breast cancer, decreased androgen production may be advantageous in terms of androgen receptor (AR)-positive breast cancers." (PMID 27706226, 2016). "In addition, the fact that AR expression is associated with a good prognosis in all sub-types of breast cancer may imply that it has tumor-suppressing and thus anti-metastatic and EMT-suppressing effects." (PMID 26797644, 2016). "And while reference to ER+ (i.e., ERα+/PR−) breast cancer will still be appropriate, designation of specific double (i.e., ERα/ERβ-variant, ERα/AR, and ERβ-variant/AR) or triple (i.e., ERα, ERβ-variant, and AR) hormone receptor-positive tumors may have greater clinical significance." (PMID 24324894, 2013). "However, the androgen receptor (AR), another member of the steroid receptor family, is also largely expressed in more than 70% of breast cancers and is now clearly implicated in the pathogenesis of breast cancer." (PMID 23663520, 2013). "We hypothesised that inherited polymorphisms in genes related to sex steroid hormone synthesis, metabolism, and cell signaling could alter the function of these genes and the proteins they encode, therefore altering breast cancer risk; in this report, we present results for the AR." (PMID 16987421, 2006).